RNU12 (RNA, U12 small nuclear)
Synonyms: RNU12-1; CDAGS; RNU12L; RNU12P; SCAR33; dJ222E13.7
Gene: Small nuclear RNA gene on chromosome 22 (42,615,244 to 42,615,393, forward strand). Ensembl gene ENSG00000276027.
Pathways (Reactome):
Gene expression (Transcription): RNA polymerase II transcribes snRNA genes
Gene Ontology:
Molecular function: pre-mRNA branch point binding
Biological process: mRNA branch site recognition
Cellular component: U12 snRNP
Homologues: Orthologues: macaque U12 (99% identical), chimpanzee U12 (98% identical), pig U12 (98% identical), guinea pig RNU12 (97% identical), rabbit RNU12 (97% identical). Paralogues in human: RNU12-2P (93% identical).
Diseases named in the same sentence as RNU12 in open-access papers:
RNU12 is named in the same sentence as 9 diseases in open-access papers, as found by Europe PMC text mining. Sharing a sentence is not in itself a finding about the gene and the disease. The quoted sentences say what the papers report.
cerebellar ataxia (4 papers, 2020 to 2022). A neurological syndrome characterized by clumsy and uncoordinated movement of the limbs, trunk, and cranial muscles. "In this study, we have investigated the molecular mechanism underlying Early onset cerebellar ataxia caused by the 84C>T mutation in the RNU12 gene encoding U12 snRNA, a component of the minor spliceosome." (PMID 33577674, 2021). "Nevertheless, CAs caused by variants in non-coding DNA sequences have also been reported, like early-onset cerebellar ataxia associated with non-coding RNA, RNU12." (PMID 34224032, 2021). "Recently, an 84C>T mutation in the U12 snRNA gene (RNU12) has been shown to cause an early-onset form of cerebellar ataxia (EOCA) with autosomal recessive inheritance." (PMID 33577674, 2021). "RNU12 biallelic variants have been found so far in a single large consanguineous family in which members displayed autosomal recessively inherited early onset cerebellar ataxia, while RNU4ATAC biallelic variants have been reported in 46 families to date." (PMID 32628740, 2020).
gastric cancer (1 paper, 2023). A primary or metastatic malignant neoplasm involving the stomach. "This study revealed the gastric cancer-associated lncRNA RNU12 is a tumor-suppressor lncRNA that inhibits cancer progression via miR-575/BLID axis, which plays crucial role in gastric cancer progression and suggest that RNU12 is potential GC marker and target for GC therapy." (PMID 37160927, 2023). "qRT-PCR was utilized for determining the RNU12 expression in cell lines, 113 cases of paired gastric cancer (GC) and their adjacent normal gastric tissues." (PMID 37160927, 2023).
lymph node metastasis (1 paper, 2023). "The clinical data demonstrated a negative relationship between RNU12 expression and clinic pathologic feature-lymph node metastasis in GC patients (P < 0.05)." (PMID 37160927, 2023).
tumor (1 paper, 2023). "The GC tumor xenograft in zebrafish model was used for exploring the association of the RNU12 biological function in vivo." (PMID 37160927, 2023). "Our previous results have discovered that RNU12 was a decreased expression level in GC, suggesting that RNU12 is an essential regulator in suppressing tumor genesis." (PMID 37160927, 2023). "Our present data supported the function of RNU12 in inhabiting GC tumor progression through suppressing the cell growth, migration, invasion, as well as the proliferative ability expression with CCND1, PCNA, N-cadherin, E-cadherin, Vimentin and BCL-2." (PMID 37160927, 2023). "Here, we explored the function of RNU12 in controlling the tumor growth and progression and found that RNU12, as a sponge of miR-575, reduced miR-575 expression, regulated BLID expression and reduced GC cell proliferation and metastasis." (PMID 37160927, 2023). "RNU12 is one of long noncoding RNAs (lncRNAs) regulating the tumor progression." (PMID 37160927, 2023).
RNU12 also shares sentences with these, for which no sentence is quoted: cancer (1 paper); craniosynostosis (1); Macrocephaly (1); neurodegenerative disease (1); Obesity (1).